GAS6 (growth arrest specific 6)
Diseases named in the same sentence as GAS6 in open-access papers (continued):
Sharing a sentence is not in itself a finding about the gene and the disease.
cataract (1 paper, 2024). Partial or complete opacity of the crystalline lens of one or both eyes that decreases visual acuity and eventually results in blindness. "Individual areas under the curve (AUCs) for discriminating glaucoma patients from ICL or cataracts were 73% and 68.5% for GAS6 and 74.9% and 66.2% for SPP1, respectively." (PMID 39000104, 2024). "Using 162 individual aqueous humors samples (39 ICL, 92 cataracts, and 31 glaucoma samples), the levels in aqueous humors of GAS6 and SPP1 significantly discriminated glaucoma patients from ICL or cataracts patients (control samples)." (PMID 39000104, 2024). "Remarkably, GAS6 and SPP1 were able to distinguish glaucoma patients from ICL and cataract patients with high diagnostic ability." (PMID 39000104, 2024). "To this end, we focused on GAS6 and SPP1, which exhibited a high upregulation in sEVs from aqueous humor from cataracts and/or glaucoma patients and were validated by WB in the total content of aqueous humor." (PMID 39000104, 2024). "The combination of GAS6 and SPP1 increased the AUCs to 76.1% and 68.7% for discriminating glaucoma patients from ICL or from cataracts patients, respectively, with a sensitivity of 65.6%, and a specificity of 87.7% and 88.5%, respectively." (PMID 39000104, 2024). "The mean concentration in pg/mL for GAS6 was 416.57 in ICL, 646.89 in cataracts, and 1185.36 in glaucoma samples." (PMID 39000104, 2024). "Finally, we analyzed the ability of GAS6 and SPP1 as glaucoma aqueous humor biomarkers to discriminate glaucoma patients from ICL and cataracts controls by ELISA using a collection of 162 individual aqueous humors samples (39 ICL, 92 cataracts, and 31 glaucoma samples)." (PMID 39000104, 2024).
cerebral lesions (1 paper, 2025). "Indeed, silibinin might be considered to be a neuroprotective agent against cerebral lesions, through activation of the GAS6/Axl-SIRT1 pathways, improvement in mitochondrial function, reduction in oxidative stress and activation of apoptosis." (PMID 41441207, 2025).
chronic heart failure (1 paper, 2023). "In particular, several reports in the literature have suggested that modulating specifically the GAS6/AXL interaction would improve chronic heart failure." (PMID 36983628, 2023).
chronic hepatitis C (1 paper, 2023). "Clinical trials have demonstrated elevated GAS6 and AXL levels in patients with chronic hepatitis C (HCV) and acute liver disease (ALD)." (PMID 37108648, 2023).
Cluster headache (1 paper, 2024). A type of headache characterized by repeated attacks of unilateral pain lasting 15 to 180 minutes and associated with local autonomic signs. "In addition, MERTK ligand galectin-3 was found at increased concentration in the serum of study participants with cluster headache, whereas the levels of MERTK ligands growth arrest specific 6 and protein S unaffected." (PMID 38783191, 2024).
coeliac disease (1 paper, 2008). "In this study, genes for growth arrest-specific 6 (GAS6) and bone marrow stromal cell antigen 2 (BST2) were found to be up-regulated in active coeliac disease, and both have previously been reported to induce cell proliferation." (PMID 18691394, 2008).
Cognitive impairment (1 paper, 2018). Abnormal cognition is characterized by deficits in thinking, reasoning, or remembering. "Administration of a PKC inhibitor, B-Raf inhibitor, or knockdown of molecules in the Gas6-Tyro3-tau axis rescues spine loss and cognitive impairment of PGRN-KI mice." (PMID 29382817, 2018).
colorectal tumor (1 paper, 2016). "In summary Tyro3 is higher expressed in primary human colorectal tumors and liver metastases compared to normal tissues, whereas Gas6 is only higher expressed in liver metastases." (PMID 27486820, 2016). "Indeed, recombinant Gas6 dose-dependently induced proliferation in HCT116 colorectal tumor cells in vitro (p < 0.005)." (PMID 27486820, 2016). "When analyzing patients' overall survival it was found that neither Gas6 nor Axl expression in primary human colorectal tumors influenced overall survival or recurrence free survival." (PMID 27486820, 2016).
delirium (1 paper, 2021). A disorder characterized by confusion; inattentiveness; disorientation; illusions; hallucinations; agitation; and in some instances autonomic nervous system overactivity. "Remarkably, GAS6 concentrations at day 1 correlated with development of delirium, a manifestation associated with worse prognosis." (PMID 34344929, 2021).
diabetic cardiomyopathy (1 paper, 2024). Diabetic cardiomyopathy is a disorder of the heart muscle in people with diabetes. "Cluster 4 was enriched in genes of the ‘heart contraction’ (e.g., ACTC1, MYL3 and ACTA1) and ‘diabetic cardiomyopathy’ (e.g., TNNI3, MYH7 and GAS6)." (PMID 37766635, 2024).
diabetic foot ulcers (1 paper, 2023). "Right: Immunostaining for CD68 (green) and Gas6 (red) in diabetic foot ulcer." (PMID 38127424, 2023). "To validate these findings, we stained sections of non-diabetic foot wounds and diabetic foot ulcers with Abs against Gas6 and CD68, a macrophage marker." (PMID 38127424, 2023).
dyslipidaemia (1 paper, 2025). "Our study confirmed key proteins (PCSK9, ANGPTL3, LPA), identified potential novel targets (GSTA1, GSTA3, EPPK1, PECR, and PLA2G15), and strengthened evidence for CELSR2 and GAS6 in dyslipidaemia." (PMID 40689090, 2025).
dysmenorrhoea (1 paper, 2025). "However, we found statistically significant differences in GAS6 levels stratified by intensity of dysmenorrhea, dyspareunia in general, and dyspareunia (last 3 months)." (PMID 40943271, 2025).
End Stage Liver Disease (1 paper, 2023). Final stage of a liver disease when the liver failure is irreversible and LIVER TRANSPLANTATION is needed. "sAxl and Gas6 (data not shown), as well as sAxl/alb and Gas6/alb ratios were increasing with Child Pugh Score (CPS), model of end-stage liver disease (MELD) as well as HVPG." (PMID 37532736, 2023).
end-stage renal failure (1 paper, 2014). "In conclusion, we identify the up-regulation of Gas6/Axl signalling as a protective mechanism which reduces tubulo-interstitial apoptosis and slows progression to end-stage renal failure in the murine nephrectomy and high phosphate diet model of CKD." (PMID 25019319, 2014).
Ewing sarcoma (1 paper, 2024). A small round cell tumor that lacks morphologic, immunohistochemical, and electron microscopic evidence of neuroectodermal differentiation. "Taken together, these data support the notion that STAT6 contributes to Ewing sarcoma chemotherapy resistance, in part, by regulating GAS6 transcription." (PMID 38906855, 2024). "We next examined the transcription factor(s) governing GAS6 transcription upon chemotherapy treatment in Ewing sarcoma." (PMID 38906855, 2024). "To further examine if chemo-induced GAS6 expression contributes to TAM kinase activation in Ewing sarcoma, we next monitored GAS6 protein expression upon chemo-treatment." (PMID 38906855, 2024). "Together, these data suggest GAS6 is necessary for chemotherapy-induced activation of Akt/ERK in Ewing sarcoma cells." (PMID 38906855, 2024). "Our study reveals the chemo/JAK1/STAT6 signaling also promotes GAS6 transcription and secretion in Ewing sarcoma." (PMID 38906855, 2024). "Our identified chemotherapy-induced JAK1/STAT6/GAS6/TAM signaling contribution to chemoresistance in cancer warrants study beyond Ewing sarcoma." (PMID 38906855, 2024). "Using phospho-profiling, genetic, and biochemical approaches, our studies unravel a chemotherapy-induced mechanism for JAK1/STAT6/GAS6-mediated autocrine or paracrine signaling contributing to Ewing sarcoma chemoresistance, by activating TAM kinases and subsequent downstream Akt and ERK signaling." (PMID 38906855, 2024).
glaucoma (1 paper, 2024). Increased pressure in the eyeball due to obstruction of the outflow of aqueous humor. "Our findings revealed not only the interesting potential of sEVs aqueous humor for the determination of biomarkers with diagnostic interest but also the usefulness of GAS6 alone or in combination with SPP1 for glaucoma diagnosis." (PMID 39000104, 2024). "A patent in evaluation (P202430051) for glaucoma diagnosis based on the identification of GAS6 and SPP1 in aqueous humor resulted from the work reported in this manuscript." (PMID 39000104, 2024). "Validation of the results by WB and ELISA allowed us to identify growth arrest-specific protein 6 (GAS6) and osteopontin (SPP1) as relevant biomarkers for glaucoma diagnosis in aqueous humor with the high diagnostic ability of the disease." (PMID 39000104, 2024). "Importantly, GAS6 and SPP1 showed high diagnostic ability of glaucoma, which in combination allowed for discriminating glaucoma patients from control individuals with an area under the curve of 76.1% and a sensitivity of 65.6% and a specificity of 87.7%." (PMID 39000104, 2024). "Considering that glaucoma shares characteristics and pathological mechanisms with other neurodegenerative diseases, the upregulation of GAS6 expression found in glaucomatous aqueous humor could represent an attempt to moderate retinal ganglion cell damage counteracting glaucoma progression." (PMID 39000104, 2024). "We focused on GAS6 and SPP1 because these validated dysregulated proteins in glaucoma by WB were among the most upregulated proteins found in aqueous humor." (PMID 39000104, 2024). "Furthermore, validation of the results directly with aqueous humor allowed us to identify GAS6 and SPP1 as relevant biomarkers for glaucoma diagnosis." (PMID 39000104, 2024). "In contrast, no information regarding the ability of GAS6 as a biomarker for glaucoma was found." (PMID 39000104, 2024).
Glomerular sclerosis (1 paper, 2019). Accumulation of scar tissue within the glomerulus. "Mice lacking Gas6 have been shown to be protected from glomerular injury, crescent formation, and glomerular sclerosis." (PMID 30742665, 2019).
Glucose intolerance (1 paper, 2015). Glucose intolerance (GI) can be defined as dysglycemia that comprises both prediabetes and diabetes. "Our previous study demonstrated that plasma Gas6 levels are associated with glucose intolerance and markers of inflammation both in adults and adolescents." (PMID 26284522, 2015).
gout (1 paper, 2023). A condition characterized by painful swelling of the joints, which is caused by deposition of urate crystals. "Gas6 knockout cancelled the protectively effects of ozone on gout pain and the paw mean intensity and duty cycle of gouty mice." (PMID 38066599, 2023). "Ozone reduces inflammation and alleviates gout pain by activating AMPK to up-regulate Gas6/MerTK/SOCS3 signaling pathway." (PMID 38066599, 2023). "In this study, we proposed the molecular mechanism of ozone in the treatment of gout pain through AMPK/Gas6/MerTK/SOCS3/MMP9 for the first time." (PMID 38066599, 2023). "Compared with the gout group, ozone can significantly increase the expression of GAS6 and activate the MerTK receptor." (PMID 38066599, 2023). "Consistent with the blood sample data of gout mice, the expression level of Gas6 in the serum of patients was significantly decreased, which further confirmed the data of our animal experiment." (PMID 38066599, 2023). "Therefore, we believe that Gas6 plays a protective role in acute gout symptoms by combining with MerTK." (PMID 38066599, 2023). "We found that ozone promoted the release of GAS6 from macrophages and activated the MerTK receptor, further inducing SOCS3 expression to treat gout pain." (PMID 38066599, 2023).
graft versus host disease (1 paper, 2018). An immune system disorder that occurs after allogeneic hematopoietic stem cell transplant and is a reaction of donor immune cells against host tissues. "Gas6 is further involved in hepatic graft versus host disease (GVHD) since apoptosis of liver cells in portal spaces is significantly lower in Gas6 KO mice." (PMID 30567378, 2018).
hematoma (1 paper, 2025). A hematoma is a collection of blood from a vascular structure into an extravascular space. "Taken together, activation of the TAMreceptors-Gas6/Pros1-PtdSer pathway may provide a viable therapeutic approach toaccelerate hematoma resolution and promote neurological recovery after ICH." (PMID 41504200, 2025).
hyperuricemia (1 paper, 2023). An abnormally high level of uric acid. "Additionally, the level of Gas6 and protein S in plasma of patients with hyperuricemia was significantly higher than that of healthy contrast group." (PMID 38066599, 2023).
IgA nephropathy (1 paper, 2014). "Furthermore, Axl and Gas6 are elevated in patients with inflammatory kidney disease and IgA nephropathy." (PMID 25019319, 2014).
Infertility (1 paper, 2021). "Therefore, we conclude that GAS6 treatment in oocytes may be proposed as an adjunct therapy in the treatment of the infertility and/or subfertility of aged oocytes in women of advanced maternal age." (PMID 34310342, 2021).
ischemia reperfusion injury (1 paper, 2024). Adverse functional, metabolic, or structural changes in ischemic tissues resulting from the restoration of blood flow to the tissue (reperfusion), including swelling; hemorrhage; necrosis; and damage from free radicals. "Collectively, these findings suggest that GAS6 played a crucial role in mediating MSC-EVs-induced promotion of BMDM efferocytosis and liver injury following ischemia-reperfusion injury." (PMID 39256347, 2024).
kidney cancer (1 paper, 2019). Primary or metastatic malignant neoplasm involving the kidney. "A notable example was 786-0 kidney cancer cells, which showed high ProS1 expression but negligible Gas6 expression." (PMID 31766614, 2019).
leiomyosarcoma (1 paper, 2022). An uncommon, aggressive malignant smooth muscle neoplasm, usually occurring in post-menopausal women. "In leiomyosarcoma patients, especially those whom develop metastasis, express higher levels of Tyro3 and Gas6, and crizotinib and foretinib showed effective antitumor activity in leiomyosarcoma through Tyro3 and Axl deactivation." (PMID 36059952, 2022).
leukocytosis (1 paper, 2023). "Interestingly, plasma levels of Gas6 in RA patients have been reported to positively correlate with disease activity scores (DAS-28), erythrocyte sedimentation rate (ESR), leukocytosis, and IL-6." (PMID 37242486, 2023).
Lewis Lung Carcinoma (1 paper, 2019). "To assess the therapeutic potential for combination treatment targeting NF-κB and Gas6-MerTK, we injected Lewis Lung Carcinoma cells subcutaneously and treated mice with Bay 11-70852 (NF-κB inhibitor) and/or Foretinib (MerTK inhibitor)." (PMID 31903163, 2019).
liposarcoma (1 paper, 2015). A usually painless malignant tumor that arises from adipose tissue. "Taken together, these findings support an autocrine mechanism of AXL activation via GAS6 secretion in liposarcoma disease progression." (PMID 26573603, 2015).
mesothelioma (1 paper, 2020). A usually malignant and aggressive neoplasm of the mesothelium which is often associated with exposure to asbestos. "Dysregulation and activation of Gas6/AXL tyrosine kinase signaling are associated with mesothelioma progression, but the mechanisms of these AXL tumorigenic roles are poorly understood." (PMID 32992696, 2020). "A better understanding of mesothelioma biology—including GAS6/AXL signaling pathways —will likely be crucial in identifying biologically rational targets for novel therapies." (PMID 32992696, 2020). "Our previous studies indicate that activation of Gas6/AXL signaling plays essential functional roles in mesothelioma tumorigenesis." (PMID 32992696, 2020).
neuroblastoma (1 paper, 2021). Neuroblastoma (NB) is the most common solid, extracranial childhood tumor. "In this study, omentin-1 exerted neuroprotective effect against H/R injury in neuroblastoma N2a cells through activation of the GAS6/Axl signaling pathway, which is accompanied by alleviation of apoptosis and oxidative stress." (PMID 35141232, 2021).
Pan (1 paper, 2024). "Overexpression of AXL, or its ligand GAS6, is frequently associated with the mesenchymal subtype and poor prognosis in GBM, and both AXL and GAS6 are listed as cancer driver genes in a recent Pan-Cancer CPTAC study." (PMID 39087397, 2024).
papillary thyroid cancer (1 paper, 2020). "In an article published in 2002 by Ito, the incidence of Axl/Gas6 gene expression was exposed in the cases of papillary thyroid cancer in children diagnosed between 1993 and 1995 in Gomel, Belarus." (PMID 32092888, 2020).
periapical granuloma (1 paper, 2025). Chronic nonsuppurative inflammation of periapical tissue resulting from irritation following pulp disease or endodontic treatment. "Subsequently, immunohistochemical (IHC) staining unraveled elevated IL-1β expression in radical cysts (RCs) relative to periapical granulomas (PGs), whereas the expression levels of Mertk, Gas6, and IL-10 were more pronounced in PGs than in RCs." (PMID 41155449, 2025).
pheochromocytoma (1 paper, 2014). "Our previous study showed that the ligand of TAM receptors, Gas6, protected the PC12 cells (derived from a pheochromocytoma of the rat adrenal medulla) from the serum- and NGF-deprivation induced apoptosis." (PMID 25514676, 2014).
proliferative glomerulonephritis (1 paper, 2019). A constellation of renal disorders characterized by an increase number of cells in the glomerulus; these disorders generally present with nephrotic syndrome, and generally progress to end stage renal failure over a matter of weeks to years, depending on the etiology. "Axl and Gas6 have also been demonstrated to be expressed by mesangial cells in glomeruli during their proliferation in a study utilising an experimental proliferative glomerulonephritis model." (PMID 30742665, 2019).
pulmonary hypertension (1 paper, 2020). Increased pressure within the pulmonary circulation due to lung or heart disorder. "We compared the median values of Gas6, sAxl, and sMer according to the presence of pulmonary hypertension." (PMID 32454903, 2020).
rheumatic diseases (1 paper, 2016). "Changes in the plasma concentration of Axl/Gas6 have been reported in rheumatic diseases such as SLE48, BD46, 47 and RA49." (PMID 27222359, 2016).
sarcoma (1 paper, 2020). A usually aggressive malignant neoplasm of the soft tissue or bone. "In contrast to other sarcoma cells, GAS6 treatment did not affect the proliferation of the MPNST cell lines, measured by MTS assay." (PMID 33283192, 2020).
silicosis (1 paper, 2021). Silicosis is a respiratory disease caused by breathing in (inhaling) silica dust. "Furthermore, an increased secretion of growth arrest-specific protein 6 (Gas6) and its typical receptor Mer has been observed in the bronchoalveolar lavage fluid of the silicosis mice model." (PMID 34360876, 2021).
Sjögren Syndrome (1 paper, 2015). "The aim of this study was to assess the implications of Gas6 in Sjögren syndrome (SS) and its expression in the labial salivary gland." (PMID 26445266, 2015). "Multivariate linear regression analyses of plasma Gas6 concentration among Sjögren syndrome." (PMID 26445266, 2015).
Splenomegaly (1 paper, 2025). Abnormal increased size of the spleen. "In addition, HCQ treatment significantly attenuated splenomegaly observed in PIL mice, accompanied by increased expression of MerTK and Gas6 in the spleen, suggesting that HCQ may promote restoration of efficient efferocytosis systemically." (PMID 40589760, 2025).
squamous cell carcinoma (1 paper, 2015). A carcinoma arising from squamous epithelial cells. "For other types of squamous cell carcinoma, researchers have found Gas6/Axl signaling overexpression, for example, in human esophageal squamous cell carcinoma samples (ESCC) and ESCC cell lines." (PMID 26207647, 2015).